LRRC49 (leucine rich repeat containing 49)
Description:
Subunit of the tubulin polyglutamylase complex (TPGC). The complex mediates cilia and flagella polyglutamylation which is essential for their biogenesis and motility.
Synonyms: PGs4; CSTPP2; FLJ20156
Tractability: PROTAC: ubiquitination databases record sites on it; its protein half-life has been measured.
Gene: Protein-coding gene on chromosome 15 (70,853,239 to 71,053,658, forward strand). Ensembl gene ENSG00000137821.
Subcellular location: Cytoplasm, cytoskeleton; Cytoplasm, cytoskeleton, microtubule organizing center, centrosome, centriolar satellite
Pathways (Reactome):
Metabolism of proteins: Carboxyterminal post-translational modifications of tubulin
Gene Ontology:
Cellular component: centriolar satellite; catalytic complex; microtubule; cytoskeleton
Genetic constraint (gnomAD): Loss-of-function variants: 19 observed, 33.18 expected, observed/expected ratio (o/e) 0.57, 90% interval 0.4 to 0.84. The upper end of that interval is the gene's LOEUF score, 0.84, which puts it in group 3 of 6, group 1 being the genes least tolerant of losing a copy. Missense variants: 379 observed, 442.64 expected, observed/expected ratio (o/e) 0.86, 90% interval 0.79 to 0.93. Synonymous variants: 142 observed, 160.52 expected, observed/expected ratio (o/e) 0.88, 90% interval 0.77 to 1.02.
Homologues: Orthologues: chimpanzee LRRC49 (99% identical), macaque LRRC49 (99% identical), pig LRRC49 (93% identical), dog LRRC49 (93% identical), guinea pig LRRC49 (92% identical), rabbit LRRC49 (90% identical), rat Lrrc49 (90% identical), mouse Lrrc49 (89% identical), tropical clawed frog lrrc49 (67% identical), Drosophila melanogaster CG13708 (29% identical). Paralogues in human: LRRC9 (21% identical), LRGUK (14% identical), LRRCC1 (14% identical), DRC3 (12% identical), DNAAF1 (12% identical), LRRC43 (11% identical), CEP97 (10% identical), DNAAF11 (10% identical), LRRIQ3 (9% identical), PPP1R42 (9% identical), LRRC61 (8% identical), LRRC46 (8% identical), and 1 more.
Diseases named in the same sentence as LRRC49 in open-access papers:
LRRC49 is named in the same sentence as 4 diseases in open-access papers, as found by Europe PMC text mining. Sharing a sentence is not in itself a finding about the gene and the disease. The quoted sentences say what the papers report.
breast carcinoma (3 papers, 2013 to 2022). "THAP1 has been associated with DYT6 dystonia, THAP5 and THAP1 have been linked to apoptosis, the LRRC49/THAP10 bidirectional gene pair is involved in breast cancer, and THAP11 has been implicated in colon and gastric cancers." (PMID 35893234, 2022). "The LRRC49 gene has been linked to breast cancer in humans, but very little is known about the biological function of the protein encoded by this gene." (PMID 23738659, 2013). "The LRRC49/THAP10 bidirectional gene pair is reported to have reduced expression in breast cancer." (PMID 35893234, 2022). "THAP10 and LRRC49 (leucine rich repeat containing 49), both located on chromosome 15q23 in close proximity, were simultaneously suppressed due to hypermethylation of the bidirectional promoter region in breast cancer." (PMID 28539478, 2017).
LRRC49 also shares sentences with these, for which no sentence is quoted: ciliopathies (1 paper); gastric cancer (1); lymphoid neoplasm (1).